FABP4 (fatty acid binding protein 4)
Diseases named in the same sentence as FABP4 in open-access papers (continued):
Sharing a sentence is not in itself a finding about the gene and the disease.
atherosclerosis (continued). "However, it is clearly necessary to prospectively evaluate whether a change in the FABP4 value indeed reflects conditions of metabolic syndrome and atherosclerosis and predicts long-term cardiovascular outcomes in patients regardless of ESRD." (PMID 22102888, 2011). "Based on epidemiological studies and animal knockout models, the isoforms FABP4 and FABP5 were identified as potential diabetes and atherosclerosis targets (reviewed in Furuhashi & Hotamisligil, 2008 ▸)." (PMID 40748031, 2025). "Pharmacological inhibition of FABP4 with compounds such as BMS309403 enhances eNOS expression and improves EC function, reducing plasma triglyceride (TG) levels and atherosclerosis progression in diabetic models." (PMID 40890841, 2025). "FABP4 and CD36 interacted closely, further confirming that FABP4 and CD36 were important mediating targets of atherosclerosis." (PMID 40824771, 2025). "Similar to BAT-like characteristics, exercise suppressed WAT-like characteristics of FABP4 expression in PVAT, thereby reversing adipocyte phenotype shift and developing atherosclerosis in obese rats." (PMID 38784129, 2024). "Atorvastatin inhibits atherosclerosis and NSCLC by down-regulating the expression of MMP9, MMP12, FABP4, and CD36." (PMID 37978381, 2023). "In conclusion, this meta-analysis examined circulating FABP-4 levels in CD patients, particularly CAD and atherosclerosis." (PMID 38024104, 2023). "FABP5 plays important roles in the development of several chronic diseases including cardiovascular disease where, as found for FABP4, macrophage-specific deletion of FABP5 was protective against development of atherosclerosis." (PMID 37207357, 2023). "Therefore, reducing FABP4 might be a potential treatment for atherosclerosis." (PMID 37978381, 2023). "This study conducted a systematic review and meta-analysis to examine FABP-4 levels in CAD and atherosclerosis patients, exploring their potential links to these conditions." (PMID 38024104, 2023). "In conclusion, MMP9, MMP12, FABP4, and CD36 genes are closely related to the occurrence and development of atherosclerosis and NSCLC." (PMID 37978381, 2023). "Previous studies have shown that fatty acid binding protein 4 (FABP4) plays an important role in macrophage inflammation and lipid metabolism in atherosclerosis induced by Hcy." (PMID 34725437, 2022). "The fourth upregulated gene, fatty acid-binding protein 4 (FABP4) has been shown to be important in macrophage cholesterol trafficking, inducing foam cell formation and the development of atherosclerosis." (PMID 34055930, 2021). "Moreover, FABP4 per se may directly contribute to atherosclerosis and/or cardiovascular damage, independent of classical risk factors." (PMID 33597568, 2021). "Moreover, apolipoprotein-E-deficient mice with FABP4 deficiency were found to be protected against atherosclerosis with or without induction by high-cholesterol Western diets, but how FABP4 deficiency can alter insulin resistance and lipid metabolism remain to be revealed." (PMID 33105856, 2020). "Mice that are knockout for both the adipocyte and epidermal fatty acid-binding protein (FABP4 and FABP5, respectively) are protected against the metabolic syndrome and atherosclerosis." (PMID 23349676, 2013). "Thus, the relationship between FABP4 level and progression of atherosclerosis remains unclear." (PMID 22102888, 2011). "It has been demonstrated that both FABP4 and FABP5 play important roles in the regulation of insulin sensitivity and the development of atherosclerosis and that their impacts differentially involve adipocytes or macrophages." (PMID 22121495, 2011). "Thus, KGs of NK cells for hawthorn's effects on the PVAT microenvironment of atherosclerosis were JUN, CXCR4, CD36, GNLY, and FABP4." (PMID 40824771, 2025). "Furthermore, our study outcomes indicate that metformin reduces FABP4 expression, thereby limiting the nuclear translocation of FOXO1 in atherosclerosis." (PMID 41471323, 2025).
atherosclerosis (continued). "Conversely, downregulation of FABP4 by apelin/apelin receptor (APLNR)-mediated Forkhead box O1 (FOXO1) suppression in ECs limits excessive FA transport and tissue accumulation, contributing to atheroprotecton against vascular diseases such as atherosclerosis." (PMID 40890841, 2025). "A drug intervention study in atherosclerotic mice demonstrated that an orally active small-molecule inhibitor of FABP4, BMS309403 (see also “Known drugs and compounds inhibiting FABP4”), was an effective therapeutic agent against severe atherosclerosis and type 2 diabetes in mouse models." (PMID 38698167, 2024). "We hypothesized that atorvastatin could inhibit the expression of MMP9, MMP12, FABP4, and CD36 in patients with atherosclerosis and NSCLC." (PMID 37978381, 2023). "In general, in recent years, several studies on the relationship between FABP-4, atherosclerosis, and CAD, though the results were not consistent, have been conducted." (PMID 38024104, 2023). "MMP9, MMP12, FABP4, and CD36 might be the potential therapeutic targets in treating atherosclerosis and NSCLC." (PMID 37978381, 2023). "It is thought that FABP4 does not play a role in atherosclerosis development in patients with hypothyroidism without metabolic disorder." (PMID 31651119, 2019). "FABP4 has a well-established role in the development and progression of diabetes and atherosclerosis, but the effect of FABP4 in AKI has not been determined." (PMID 35541316, 2018). "However, little is known about the link between CEC and levels of FABP4 and FABP5 regarding the development of atherosclerosis." (PMID 28303004, 2017). "Upregulation of FABP4 (fatty acid binding protein 4) further enhances the macrophage lipid accumulation by advanced glycation end products (AGE), which further accelerates formation of foam cells and development of atherosclerosis in diabetic patients." (PMID 28761062, 2017). "Additionally, FOXO1 has indispensable role in positive regulation of adipocyte fatty acid binding protein (FABP4) gene transcription, thereby controlling uptake and accumulation of lipids in macrophages, and promoting atherosclerosis." (PMID 26956801, 2016). "Interestingly, LPL (lipoprotein lipase, 1,001 fold), APOE (apolipoprotein E, 778 fold), FABP4 (fatty acid binding protein 4, 680 fold), and APOC1 (apolipoprotein C–I, 614 fold) are atherosclerosis related genes in which activated monocytes play a role." (PMID 23844045, 2013). "The international databases including Medline, Embase, Cochrane Library, Scopus, Web of Science, and UpToDate were searched to find all related studies on the effect of FABP-4 on patients with CAD or atherosclerosis which were published till June 2022 without language restriction." (PMID 38024104, 2023). "Fatty acid binding protein 4 (FABP4; alternatively called adipocyte protein 2, aP2), which is mainly expressed in adipocytes and macrophages, plays an important role in the development of insulin resistance and atherosclerosis in relation to metabolically driven chronic inflammation." (PMID 35740306, 2022). "Mice lacking the Fabp4 gene have a lower chance of developing atherosclerosis." (PMID 36060264, 2022). "However, in our study, atherosclerosis did not change either the myocardial content of FABP4 protein or the intracellular free fatty acids content." (PMID 31979197, 2020). "FABP4 in dendritic cells has been shown to regulate the IKK-NF-κB pathway and T-cell priming, which might contribute to the development of atherosclerosis since there is clear evidence for the involvement of both dendritic and T cells in the pathogenesis of atherosclerosis." (PMID 22121495, 2011). "Another scientific group investigating the effect of Hcy on fatty acid binding protein 4 (FABP4) suggested that FABP4 plays a key role in Hcy mediated disturbance of lipid metabolism and that DNA methyltransferase 1 (DNMT1) may be a novel therapeutic target in Hcy-related atherosclerosis." (PMID 27932944, 2016).
atherosclerosis (continued). "Previous studies have indicated that macrophage regulation involves the FABP4 and FOXO1 pathways in an atherosclerosis model; however, these mechanisms have not been confirmed in a DN model, representing a critical gap in the literature." (PMID 41471323, 2025). "Interestingly, the concentration of FABP5, but not that of FABP4, has been reported to be negatively and independently associated with cholesterol efflux capacity from macrophages as a function of HDL cholesterol, suggesting a potential residual risk biomarker in atherosclerosis." (PMID 33071982, 2020).
diabetes (155 papers, 2011 to 2025). "Here, we demonstrated that FABP4 deficiency ameliorated STZ‐induced diabetes onset, insulitis, activation, and imbalance of T lymphocytes in C57BL/6N mice." (PMID 40716098, 2025). "While literature indicates that FABP4 levels increase in atherosclerotic diseases, a meta-analysis found that a 1-SD decrease in FABP4 among Type 1 diabetes mellitus patients increased the risk of CAD by 2.4-fold." (PMID 41187309, 2025). "FABP4, as implicated in diabetes-induced MAFLD, represents a promising target for future studies aimed at developing therapeutic interventions for MAFLD or strategies to prevent the progression to NASH and liver fibrosis." (PMID 39494341, 2024). "As shown in previous research, FABP-4 is highly expressed in adipocytes, and its increased levels have been associated with adiposity, hypertension and diabetes." (PMID 39711764, 2024). "Hormonal FABP4 has a strong positive correlation with BMI and is associated with numerous metabolic disorders, including diabetes, cardiovascular disease, and various types of cancers." (PMID 37172691, 2023). "Elevated serum levels of FABP4 are also associated with obesity, diabetes mellitus, hypertension, and cardiovascular events." (PMID 32075656, 2020). "Another study identified a correlation between FABP4 and impaired endothelial function in diabetes, which lead to an increased cardiovascular risk." (PMID 30857223, 2019). "A genetic polymorphism in the FABP4 promoter region results in diminished FABP4 expression in adipose tissue, and has been associated with reduced risk of diabetes and cardiovascular disease in man." (PMID 23122912, 2013). "While there is no known direct link between FABP4 and coronavirus infections, FABP4 is known to promote inflammation and metabolic dysfunction in several comorbidities that constitute a high-risk for coronavirus infection, including diabetes, cardiovascular disease, and airway disease." (PMID 39843629, 2025). "Other studies show association of FABP4 levels with elongated QT intervals in patients with stable angina and kidney disease, but also with rapid renal functional decline in patients with diabetes." (PMID 38698167, 2024). "Specifically, serum FABP4 concentrations correlate positively with the HF biomarker N-terminal fragment of pro-B-type natriuretic peptide (NT-proBNP), this association being even stronger in subjects with diabetes and HF." (PMID 36978893, 2023). "Furthermore, FABP4 was positively associated with age, BMI, diabetes mellitus, hypertension, hyperlipidemia, SBP, LDL-C, triglycerides, creatinine, and FABP3." (PMID 37255976, 2023). "Moreover, we found positive associations between plasma FABP4 with BMI, diabetes mellitus, hypertension, SBP, LDL-C, triglycerides, creatinine, and FABP3, and negative associations between plasma FABP4 with HDL-C, eGFR, and HF HRV." (PMID 37255976, 2023). "Moreover, positive associations between FABP4 with body mass index, diabetes mellitus, hypertension, systolic blood pressure, low-density lipoprotein-cholesterol, triglycerides, creatinine, and FABP3 were found." (PMID 37255976, 2023). "Furthermore, a sex and age-adjusted multiple linear regression model revealed a positive association between FABP4 with BMI, diabetes mellitus, hypertension, SBP, LDL-C, triglycerides, creatinine, and FABP3." (PMID 37255976, 2023). "Diabetes was associated with increased nuclei per tissue area and suppressed levels of adipogenesis-associated genes, including Pparg, Cepba, Fabp4, Lpl, and Adipoq." (PMID 36307522, 2022). "Clinical studies point out that serum FABP4 is positively associated with the degree of abdominal aortic calcification in peritoneal dialysis patients as well as with the presence of coronary artery calcium in patients with type-2 diabetes mellitus." (PMID 35955575, 2022). "Based on the existing evidence, the reduction in FABP4 levels may improve insulin sensitivity and lower diabetes risk." (PMID 34368366, 2021).
diabetes (continued). "Furthermore, the expression of FABP4 in adipocytes has been positively associated with mortality, incident diabetes mellitus, greater coronary plaque burden, coronary artery disease (CAD), and heart failure (HF)." (PMID 31234795, 2019). "Tbc1d4, Acadl, Acsl1 and Fabp4 were found to be associated with early diabetes in GK rats for the first time, which may provide a new scope for pathogenesis of postprandial hyperglycemia." (PMID 31141985, 2019). "Furthermore, researchers from Hong Kong also documented that among patients with diabetes mellitus, serum FABP4 levels were shown to be independently associated with the severity of nephropathy." (PMID 30857223, 2019). "While this requires further investigation, a thorough examination of FABP4’s engagement in these pathways could have important implications for mitigating the risk of developing diabetes or sustaining long-term respiratory symptoms, both documented amongst the many symptoms of long-COVID." (PMID 39843629, 2025). "Circulating FABP4 levels exhibit a strong positive correlation with diabetes and cardiovascular disease, and multiple independent genome-wide association studies have identified protection in individuals with a low-expression variant of FABP4 against type 2 diabetes and cardiovascular diseases." (PMID 37172691, 2023). "Circulating FABP4 levels can be also associated with the clinical presence of myocardial ischemia, atherogenic dyslipidemia, and type 2 diabetes mellitus (DM)." (PMID 33287461, 2020). "Therefore, we sought to assess whether circulating FABP4 is independently associated with PAD in patients with diabetes, and its potential to serve as a diagnostic biomarker in this regard." (PMID 32887447, 2020). "This is the first study that suggests Tbc1d4, Acadl, Acsl1 and Fabp4 are associated with early diabetes in GK rats, which may provide a new scope for pathogenesis of postprandial hyperglycemia and controlling postprandial glucose levels in T2D patients at early stages." (PMID 31141985, 2019). "Its elevated expression in diabetes is thought to result from early oxidative stress and inflammation, leading to active macrophage accumulation and high serum FABP4 levels." (PMID 41471323, 2025). "A connection has been established between higher levels of FABP4 and gestational diabetes mellitus and type 2 diabetes mellitus (T2DM), suggesting that its potential as a therapeutic target." (PMID 41471323, 2025). "Keeping in view the Nrf2 and FABP4 independent roles among diabetes, only a few reports are available about the Nrf2 and FABP4 roles among PAD-T2DM patients." (PMID 40728998, 2025). "The results indicated that in cases with high expression of FABP4, CDR2L, and FSTL3, immune-related pathways associated with diabetes and colon cancer were significantly enriched." (PMID 40595026, 2025). "Elevated levels of FABP4 have also shown a strong correlation with the deterioration of kidney function in diabetes patients." (PMID 38731797, 2024). "In the current study, we found that plasma FABP4 levels were significantly high among patients with diabetes and increased body weight." (PMID 38731797, 2024). "On the other hand, FABP4 has been identified as a key molecule in oxidative stress during MI/R injury and diabetes-induced cardiac dysfunction in FABP4-knockout mice." (PMID 36978893, 2023). "Some studies have shown that FABP-4 can predict the development of metabolic syndrome (MetS) and type 2 diabetes mellitus." (PMID 38024104, 2023). "Recently, FABP4 has also been related to ectopic fat accumulation in the heart, one of the main precursors of myocardial dysfunction due to diabetes." (PMID 36978893, 2023). "FABP4 is a novel adipokine that regulates inflammation and angiogenesis and plays a central role in controlling lipolysis and the development of diabetes." (PMID 37180113, 2023). "It did not account for medication usage, genetic factors, lifestyle variables, or diabetes-related factors that can influence FABP-4 levels." (PMID 38024104, 2023).